USP22 (ubiquitin specific peptidase 22)
Diseases named in the same sentence as USP22 in open-access papers (continued):
Sharing a sentence is not in itself a finding about the gene and the disease.
colon carcinoma (11 papers, 2015 to 2025). "To study the underlying molecular mechanisms of USP22/CCNB1 crosstalk in colon cancer development, we first confirmed their interaction." (PMID 27030811, 2015). "Interestingly, loss of USP22 expression increased H2Bub1 levels in HT‐29 colon carcinoma cells, which is in agreement with previous studies." (PMID 33369872, 2021). "USP22 is highly expressed in many types of human cancers, including colon cancer; however, the physiological functions of USP22 and its role in tumorigenesis, as well as the underlying molecular mechanisms resulting in both normal and abnormal cell cycle regulation, are largely unknown." (PMID 27030811, 2015). "Here, the functional consequences of USP22 on PML expression levels were investigated by CRISPR/Cas9-mediated constitutive knock-out (KO) of USP22 in the human HT-29 colon carcinoma cell line, generated." (PMID 38467608, 2024). "To validate this observation, we assessed the expression of USP22 following Taz treatment in various colon cancer cell lines." (PMID 38520088, 2024). "Taz enhanced USP22 expression at both the mRNA and protein levels in various colon cancer cell lines, including HCT116, SW480, LS180, and MC38 cells." (PMID 38520088, 2024). "By contrast, the deubiquitinating enzyme USP22 promotes PD-L1 stabilization in colon cancer (COAD), while EZH2 inhibits USP22 transcription via H3K27me3, leading to PD-L1 degradation." (PMID 39080807, 2024). "Since necroptosis represents an attractive alternative for overcoming apoptosis resistance in colon cancer, we therefore aimed to investigate the functional role of USP22 during necroptosis." (PMID 33369872, 2021). "Relevant to our study is the observation that USP22 has tumor suppressive functions in colon cancer by reducing mTor activity." (PMID 33629655, 2021). "Our discovery here, that both USP22 and CCNB1 proteins are elevated and positively associated in human colon cancers, indicates that USP22-mediated CCNB1 stabilization is one possible molecular mechanism underlying its proto-oncogenicity." (PMID 27030811, 2015). "Elevated levels of both CCNB1 and USP22 indicate more aggressive cancer and a poor prognosis and both of these proteins were upregulated in colon cancer patients." (PMID 27030811, 2015). "Most importantly, our observation that USP22 knockdown impairs human cancer cell growth and tumor formation suggests that USP22 is involved in tumorigenesis, implying a great therapeutic potential of USP22 suppression in colon cancer treatment." (PMID 27030811, 2015). "In fact, immunoblotting analysis confirmed dramatically higher protein expression levels of both CCNB1 and USP22 in colon cancer tissues (in 7 of 10 patients) compared with those in adjacent normal controls." (PMID 27030811, 2015). "A soft agar assay revealed that stable expression of USP22 dramatically enhanced the colony formation of HCT116 cells while USP22 knockdown resulted in fewer colonies, suggesting that USP22 plays an important role in colon cancer cell growth." (PMID 27030811, 2015). "In addition, knocking down USP22 can potentially enhance the therapeutic efficacy of EZH2 inhibitors on colon cancer." (PMID 38520088, 2024). "USP22 is highly expressed in various colon carcinoma cell lines and mediates apoptosis resistance." (PMID 33369872, 2021). "Upregulation of either CCNB1 or USP22 has been found in human colon cancers." (PMID 27030811, 2015). "Therefore, USP22 expression is critical for colon cancer growth, as tested both in vitro and in the xenograft mouse model." (PMID 27030811, 2015). "Next, we questioned whether USP22 is involved in the elevated CCNB1 protein expression in human colon cancers." (PMID 27030811, 2015). "Our data indicate a great therapeutic potential of USP22 suppression in human colon cancer therapy." (PMID 27030811, 2015). "Hence, we determined whether downregulation of USP22 suppresses colon cancer cell growth and cancer progression." (PMID 27030811, 2015).
colon carcinoma (continued). "Therefore, USP22 is an interacting partner of CCNB1 in human colon cancer cells." (PMID 27030811, 2015). "Thus, our study identified USP22 as an interacting protein of CCNB1 in human colon cancer cells." (PMID 27030811, 2015). "The interaction between endogenous USP22 and CCNB1 in human colon cancer cells was also detected, as anti-CCNB1-specific antibody but not normal mouse immunoglobulin G immunoprecipitated USP22 protein." (PMID 27030811, 2015). "On the one hand, USP22 is a CCNB1 deubiquitinase that promotes cell cycle progression and colon cancer cell growth." (PMID 27030811, 2015). "First, both USP22 and CCNB1 protein expression are elevated with a strong positive correlation in human colon cancer tissues." (PMID 27030811, 2015). "Herein, we identify USP22 as a CCNB1 interactor and discover that both USP22 and CCNB1 are dramatically elevated with a strong positive correlation in colon cancer tissues." (PMID 27030811, 2015). "As both USP22 and CCNB1 are upregulated and positively correlated in colon cancer, targeting either of them might be a good approach to cancer therapy." (PMID 27030811, 2015). "Furthermore, we find a positive correlation between USP22 and CCNB1 expression in human colon cancers." (PMID 27030811, 2015). "We previously reported that CRISPR/Cas9-mediated knockout (KO) of USP22 in the human colon carcinoma cell line HT-29 affects RIPK3 ubiquitination during necroptosis without inducing major changes in RIPK1, RIPK3, and MLKL gene expression, suggesting gene-specific regulation of USP22." (PMID 35933402, 2022). "In addition, given the fact that USP22 is abnormally upregulated and there are gene alterations in several components of the APC/C complex in human colon cancers, it will be interesting to investigate whether these two events are positively associated." (PMID 27030811, 2015).
melanoma (11 papers, 2011 to 2026). A malignant, usually aggressive tumor composed of atypical, neoplastic melanocytes. "To investigate the potential oncogenic mechanism of USP22, we initially generated USP22‐deficient melanoma cells via CRISPR–Cas9 technology and observed minimal suppression of cell proliferation, as detected by CCK‐8 assay." (PMID 39135915, 2024). "USP22 demonstrates a strong association with poor clinical outcomes and is significantly overexpressed in melanoma." (PMID 39135915, 2024). "Consistently, H&E images showed that USP22 loss significantly impaired melanoma lung metastasis with less metastatic foci." (PMID 39135915, 2024). "The shorter migrated distance and delayed wound repair were detected in USP22‐deficient melanoma cells." (PMID 39135915, 2024). "We observed that USP22 knockout has a minimal effect on the growth of xenografted melanoma tumors, and the bodyweight of mice is comparable between the USP22‐deficient and control groups." (PMID 39135915, 2024). "To further validate the association between USP22 expression and poor prognosis in melanoma, we performed Kaplan–Meier analysis and found that elevated USP22 expression is significantly linked with shortened overall survival and disease‐specific survival." (PMID 39135915, 2024). "USP22 expression is highly upregulated in melanoma and positively associated with the pathological stage of melanoma, suggesting the potential of USP22 as a diagnostic and prognostic biomarker for melanoma." (PMID 39135915, 2024). "Western blotting assay revealed elevated levels of the epithelial marker E‐cadherin protein and reduced levels of the mesenchymal markers vimentin and SNAL1 protein in USP22‐deficient melanoma cells." (PMID 39135915, 2024). "Consistently, topotecan treatment decreased SIRT1 expression, phosphorylation of Akt at Ser473 and mTOR at Ser2448, as well as EMT activity, but had minimal effects in USP22‐deficient melanoma cells." (PMID 39135915, 2024). "Ubiquitin-specific peptidase 22 (USP22) is a novel DUB in melanoma that has been linked to cell cycle progression, treatment resistance, metastasis, and immune response." (PMID 35884430, 2022). "Similarly, the number of invasive melanoma cells was significantly reduced in both USP22‐deficient melanoma cells and USP22 knockdown cells with siRNA." (PMID 39135915, 2024). "Recently, knockdown of USP22 in reduced melanoma cells has been associated with cell proliferation." (PMID 35884430, 2022). "USP22 is widely regarded as an oncoprotein; its aberrant expression has been associated with poor cancer prognosis in various types of human cancer, including melanoma patients." (PMID 35884430, 2022). "However, the role of USP22 in ferroptosis susceptibility in melanoma remains elusive." (PMID 39135915, 2024). "However, a comprehensive understanding of the role and underlying mechanisms by which USP22 regulates melanoma metastasis is often overlooked and remains largely unknown." (PMID 39135915, 2024). "Pharmacological inhibition of USP22 by topotecan exerts a similar effect to USP22 knockout in inhibiting melanoma metastasis both in vivo and in vitro." (PMID 39135915, 2024). "Conversely, USP22‐overexpressing melanoma cells exhibited an increased number of migrative and invasive melanoma cells compared with control cells." (PMID 39135915, 2024). "Together, our results demonstrated the upregulation of USP22 in melanoma and its correlation with poor clinical outcomes." (PMID 39135915, 2024). "We also detected USP22 expression in melanoma cell lines and melanocyte (PIG1), with high expression in melanoma cells but relatively low expression in melanocytes." (PMID 39135915, 2024). "Here, we identified ubiquitin‐specific protease 22 (USP22) as a pro‐oncogenic protein in melanoma through screening the survival profiles of 52 ubiquitin‐specific proteases (USPs)." (PMID 39135915, 2024).
melanoma (continued). "In this study, we identified USP22 is overexpressed in melanoma and facilitates melanoma metastasis in vitro and in vivo." (PMID 39135915, 2024). "In this study, by analyzing the profile survival of 52 USPs, we identified USP22 as a predictor for poor prognosis in melanoma." (PMID 39135915, 2024). "To further verify USP22 protein levels in melanoma, we performed immunohistochemistry (IHC) staining and detected markedly higher intensities of USP22 immunostaining in melanoma compared with normal tissues." (PMID 39135915, 2024). "Overall, our findings reveal a prometastatic role of USP22 and identify topotecan as a potent USP22‐targeting drug to limit melanoma metastasis." (PMID 39135915, 2024). "Ablation of USP22 expression remarkably attenuates melanoma migration, invasion, and epithelial–mesenchymal transition in vitro and suppresses melanoma metastasis in vivo." (PMID 39135915, 2024). "We also constructed USP22‐overexpressing A375 and SK‐Mel‐28 melanoma cells and found that overexpression of USP22 exerts a negligible impact on melanoma cell proliferation." (PMID 39135915, 2024). "In this context, our data clearly showed that topotecan impairs the PI3K/Akt pathway and EMT through the USP22/SIRT1/PTEN axis in melanoma." (PMID 39135915, 2024). "In melanoma, USP22 interacts with and deubiquitinates YAP, thereby favoring melanoma cell proliferation." (PMID 39135915, 2024). "Taken together, these results suggested that topotecan suppresses melanoma metastasis by specifically targeting USP22." (PMID 39135915, 2024). "Cellular thermal shift assay (CETSA) confirmed that topotecan increases the thermal stability of the USP22 protein in melanoma cells, indicating that topotecan directly interacts with USP22." (PMID 39135915, 2024). "Conversely, we have substantiated a remarkable role of USP22 in promoting melanoma migration, invasion, and lung metastasis." (PMID 39135915, 2024). "In summary, our study not only illustrates the mechanism by which USP22 controls melanoma metastasis and ferroptosis through the SIRT1/PTEN/PI3K axis but also provides a basis for the treatment of melanoma metastasis by targeting USP22." (PMID 39135915, 2024). "Conversely, decreased E‐cadherin and increased vimentin and SNAL1 protein levels were detected in USP22‐overexpressing melanoma cells." (PMID 39135915, 2024). "Herein, we conducted RNA sequencing and found that USP22 promotes melanoma metastasis through the PI3K/Akt pathway." (PMID 39135915, 2024). "Our study highlights the crucial role of USP22 in melanoma metastasis, presenting it as an attractive therapeutic target." (PMID 39135915, 2024). "To date, these studies have focused on the impact of USP22 on melanoma growth and the interaction between melanoma cells and immune cells." (PMID 39135915, 2024). "Altogether, our findings indicate that targeting USP22 represents a promising avenue to treat melanoma metastasis." (PMID 39135915, 2024). "In melanoma patient samples, a correlation between USP22 and YAP was observed, and, as a result, high USP22 expression was associated with high YAP expression." (PMID 35884430, 2022). "A higher expression of USP22 has been observed in metastatic melanoma compared to that in the primary tumor, indicating an important role in melanoma progression." (PMID 35884430, 2022). "This study highlights a novel role for the tumor suppressive properties of USP22 via regulation of PD-L1, which suppressed antitumor immunity in melanoma mouse tumor models but also in other cancers." (PMID 35884430, 2022). "Inactivation of ubiquitin-specific peptidase 22 (USP22), a deubiquitinating protease, reduced the sensitivity of melanoma cells to T cell-mediated killing by regulating the IFN-JAK1-STAT1 signaling pathway." (PMID 34827646, 2021). "To determine whether USP22 affects melanoma cell migration and invasion, we employed 3D Matrigel drop invasion, wound healing and transwell assays." (PMID 39135915, 2024).
melanoma (continued). "Besides, USP22 in melanoma cells stabilizes STAT1 and promotes the interferon pathway, which improves the cytotoxic effects of CD8+ T cells." (PMID 39135915, 2024). "To determine whether USP22 activates the PI3K/Akt/mTOR pathway via SIRT1‐mediated PTEN deacetylation, we used siRNA to silence the expression of SIRT1 in USP22‐overexpressing melanoma cells." (PMID 39135915, 2024). "Finally, we explored the relationship between USP22 and melanoma vulnerability to ferroptosis and found that USP22 inhibition sensitizes melanoma to RSL3‐induced ferroptosis through inhibiting PI3K/Akt/mTOR pathway‐mediated SCD expression." (PMID 39135915, 2024). "However, our current understanding of the role of USP22 in melanoma metastasis remains largely unexplored." (PMID 39135915, 2024). "We took a further step to elucidate the role of USP22/SIRT1 interaction in melanoma metastasis." (PMID 39135915, 2024). "We firstly analyzed the pathway associated with mesenchymal stem cell differentiation based on GSE datasets (GSE15605 and GSE46517) and found that the mesenchymal stem cell differentiational pathway is significantly activated in melanoma cells with elevated USP22 expression." (PMID 39135915, 2024). "Notably, USP22 stands out as one of the most differentially expressed genes, with upregulated expression in melanoma compared with normal skin." (PMID 39135915, 2024). "Notably, USP22 protein levels were positively correlated with the pathological stage of melanoma (stage II, H‐score, 92.55 ± 4.234 vs. stage III, H‐score 108.4 ± 16.83)." (PMID 39135915, 2024). "Moreover, we found that USP22 expression is relatively elevated in melanoma when compared with normal skin or tumor‐adjacent normal tissues in Xiangya dataset and two different GSE datasets (GSE15605 and GSE46517)." (PMID 39135915, 2024). "Mechanistically, USP22 controls melanoma metastasis by targeting SIRT1/PTEN/PI3K signaling axis." (PMID 39135915, 2024). "Furthermore, our study identified topotecan as a clinical USP22‐targeting drug capable of effectively suppressing melanoma metastasis in vivo." (PMID 39135915, 2024). "Mechanistically, USP22 controls melanoma metastasis through the SIRT1/PTEN/PI3K pathway." (PMID 39135915, 2024). "However, the role of USP22 remains controversial at this stage and was challenged by a study showing that suppression of Usp22 expression in B16-OVA melanoma cells markedly reduced the immune response." (PMID 35884430, 2022). "Based on our results, the ferroptosis inhibitor liproxstatin‐1 partially rescued the inhibitory effect of topotecan on metastasis, indicating that pharmacological inhibition of USP22 could partially suppress melanoma metastasis by enhancing ferroptosis sensitivities." (PMID 39135915, 2024). "Moreover, they found deletion of the deubiquitinating protease ubiquitin specific peptidase 22 (USP22) in melanoma cells decreased the efficacy of T cell-mediated killing in vitro and in vivo, while USP22 overexpression enhanced tumor-cell sensitivity to T cell-mediated killing." (PMID 37427373, 2023). "USP22 inhibition, PI3K inhibitor (GDC‐0941), Akt inhibitor (MK‐2206), and mTOR inhibitor (AZD‐8055) strongly inhibited melanoma invasion in melanoma cells." (PMID 39135915, 2024). "We further analyzed genes associated with EMT in TCGA datasets and found a positive correlation between USP22 and EMT‐related genes across various cancer types, including melanoma." (PMID 39135915, 2024). "Hence, we hypothesized that USP22 might facilitate melanoma metastasis through promoting EMT." (PMID 39135915, 2024). "Taken together, these results suggested that inhibition of USP22 enhances ferroptosis sensitivity by downregulating SCD, thereby contributing to the reduction of melanoma metastasis." (PMID 39135915, 2024).